REG3A (regenerating family member 3 alpha)
Diseases named in the same sentence as REG3A in open-access papers (continued):
Sharing a sentence is not in itself a finding about the gene and the disease.
cancer (21 papers, 2013 to 2025). A tumor composed of atypical neoplastic, often pleomorphic cells that invade other tissues. "REG3A has been previously linked to a number of human cancers, including hepatocellular carcinoma, gastric carcinoma and CRC." (PMID 26646797, 2016). "While its impact on tumorigenesis remains to be definitively established, existing evidence suggests that REG3A may influence cancer risk by modulating microbial composition, inflammatory signaling, and epithelial integrity." (PMID 40723277, 2025). "In contrast, its involvement in cancer is complex and highly variable, with REG3A frequently dysregulated and linked to chronic inflammation, immune evasion, and aberrant cell proliferation, factors that complicate efforts to define a universal role in tumorigenesis." (PMID 40723277, 2025). "As we reviewed above, the cancer-promoting effects of Reg3A, which were mainly manifested as cell proliferation promotion, cell apoptosis inhibition, the regulation of cancer cell migration and invasion, as well as inflammation-linked pancreatic carcinogenesis, have been established." (PMID 31921694, 2019). "Increased stromal Reg3A/G expression may contribute to the reduced penetration of chemotherapy drugs in the cancer tissue, and associated with drug resistance." (PMID 27788482, 2016). "Mechanistically, REG3A influences key oncogenic signaling pathways and metabolic reprogramming, notably glucose metabolism essential for cancer cell survival and proliferation." (PMID 40723277, 2025). "This review highlights the multifaceted biology of REG3A, with a focus on its roles in epithelial defense, immune modulation, oxidative stress regulation, and its paradoxical functions in cancer." (PMID 40723277, 2025). "Collectively, these findings highlight the nuanced and highly variable nature of REG3A’s involvement in cancer." (PMID 40723277, 2025). "Rigorous preclinical and translational studies are needed to delineate its safety profile and therapeutic window before advancing REG3A-based interventions in cancer." (PMID 40723277, 2025). "These discrepancies emphasize the highly variable and adaptable role of REG3A in cancer, shaped by the inflammatory milieu and surrounding signaling networks." (PMID 40723277, 2025). "While correlations between REG3A expression and clinical outcomes have been documented across multiple cancer types, mechanistic understanding remains incomplete." (PMID 40723277, 2025). "In vivo studies on REG3A remain limited, resulting in significant gaps in our understanding of its functional roles in mammalian cancer models." (PMID 40723277, 2025). "While REG3A offers critical protection in inflammatory settings, its role in cancer is far more complex." (PMID 40723277, 2025). "Comparative analysis of REG3A studies across cancer types and experimental models (in vitro, in vivo, human cohorts)." (PMID 40723277, 2025). "These functions are essential for preserving tissue integrity and homeostasis and have consequently drawn attention to REG3A’s potential involvement in cancer biology." (PMID 40723277, 2025). "Conversely, other studies describe elevated REG3A expression in GC tissues, where its knockdown results in decreased cancer cell proliferation, migration, and invasion, indicating a potential oncogenic role under certain conditions." (PMID 40723277, 2025). "Collectively, these limitations present a substantial obstacle to fully elucidating the relevance of REG3A in cancer and underscore the need for replication studies, physiologically relevant models, and integrative research approaches." (PMID 40723277, 2025). "Several studies have shown that REG3A is highly expressed in cancer cells and promotes tumorigenesis." (PMID 34811636, 2022). "Inhibition of proliferation, induction of apoptosis, cell-cycle arrest, and repression of cell invasion and migration were observed after REG3A overexpression in cancer cells through the JAK2/STAT3 or PI3K/Akt signaling pathways." (PMID 34811636, 2022).
cancer (continued). "Here, we review the regulation, function, and potential clinical application of REG3A to identify novel therapeutic targets for cancer treatment." (PMID 34811636, 2022). "Recently, Reg3A plays crucial roles in a variety of diseases, such as lupus nephritis, polymyositis and dermatomyositis, keratinocytes, and cancers." (PMID 34605357, 2021). "In recent years, considerable attention has been focused on the tumorigenesis effects of Reg3A, which were mainly manifested as cell proliferation promotion, cell apoptosis inhibition, the regulation of cancer cell migration and invasion." (PMID 31921694, 2019). "Up to date, a large amount of evidence have shown that Reg3A mediates diverse functional effects under cancer conditions, including cell proliferation promotion, cell apoptosis inhibition, the regulation of cancer cell migration and invasion." (PMID 31921694, 2019). "Previous studies have investigated the altered expression of regenerating islet-derived 3 alpha (REG3A) in various cancers." (PMID 26646797, 2016). "Moreover, recent advances in cancer immunotherapy, alongside growing evidence that gut microbiota composition influences treatment efficacy, highlight a promising opportunity for REG3A-based microbiota modulation to enhance immunotherapeutic outcomes." (PMID 40723277, 2025). "In summary, the REG3A-microbiota–cancer axis represents a promising but largely unexplored domain." (PMID 40723277, 2025). "A deeper understanding of REG3A’s pleiotropic effects could open up new therapeutic avenues in both inflammatory disorders and cancer." (PMID 40723277, 2025). "Recently, the role of REG3A in cancer has received increasing attention." (PMID 34811636, 2022). "Taken together, better understanding of REG3A may lead to new insights that make it a potentially useful target for cancer therapy." (PMID 34811636, 2022). "In addition, the role of REG3A in cancer is receiving increasing attention, as it is expressed in many tumors." (PMID 34811636, 2022). "Some studies have demonstrated that high expression of REG3A in cancers can be oncogenic." (PMID 34811636, 2022). "The effect of Reg3A on a variety of human cancers has been gradually recognized in recent years." (PMID 34605357, 2021). "Moreover, we demonstrate the functional importance of this mechanism, showing that REG1CP promotes cancer cell proliferation and tumorigenicity through activation of REG3A." (PMID 31767869, 2019). "Therefore, further studies in more cancer cell lines are required to elucidate the exact effect of Reg3A on proliferation of gastrointestinal cancer cells." (PMID 31921694, 2019). "A previous study demonstrated that REG3A treatment increases the deposition of collagen and fibronectin of PSCs, which suggested that it may be involved in cancer progression." (PMID 26646797, 2016). "However, it remains difficult to determine whether REG3A actively promotes cancer or simply responds to changes in inflammation." (PMID 40723277, 2025). "Therefore, the significantly high expression of REG3A implies that it could play an oncogenic role in various cancers." (PMID 34811636, 2022). "Thus, REG3A may act as a suppressive factor in these types of cancer, and the downregulation of REG3A may be useful in the diagnosis of such cancers." (PMID 34811636, 2022). "Therefore, the possible roles of Reg3A in other types of cancer need to be investigated." (PMID 31921694, 2019). "REG3A, a key member of the human REG lectin family, plays a multifaceted role in immunity, inflammation, and cancer." (PMID 40723277, 2025). "Both studies relied on large-scale cohorts, yet they reported opposing correlations between REG3A expression and cancer progression, one showing a negative correlation and the other a positive association." (PMID 40723277, 2025). "REG3A, a prominent member of the human regenerating islet-derived (REG) lectin family, plays a pivotal and multifaceted role in immune defense, inflammation, and cancer biology." (PMID 40723277, 2025).
cancer (continued). "Clinically, cirrhotic patients with high hepatic REG3A have longer cancer-free survival, although REG3A levels do not affect outcomes once HCC develops." (PMID 40723277, 2025). "Immunohistochemically, the infiltrative PDAC cancer glands stained strongly positive for Reg1A and Reg1B, but negative for Reg3A/G." (PMID 27788482, 2016). "However, other studies have demonstrated low levels of REG3A expression in cancer cells and a negative correlation with cancer progression." (PMID 34811636, 2022). "Moreover, overexpression of REG3A reversed the reduction in growth of LIM1215-shREG1CP xenografts in nu/nu mice treated with Dox, consistent with the notion that REG1CP functions through REG3A to sustain cancer cell proliferation in vivo." (PMID 31767869, 2019).
infection (12 papers, 2013 to 2025). The state of being infected such as from the introduction of a foreign agent such as serum, vaccine, antigenic substance or organism. "Regenerating islet-derived protein 3A (Reg3a) is a bactericidal, gut-specific protein that is often secreted in response to inflammation during the acute phase of infection to protect the gut epithelium." (PMID 38430452, 2024). "Reg3a and Reg3g are C-type lectins expressed in the intestinal epithelial cells and secreted into the intestinal lumen and exert bactericidal action, thus Reg3a and Reg3g were considered to provide protection against infection with enteropathogenic bacteria." (PMID 37170509, 2023). "Surprisingly, in our cohort of Asian macaques, plasma levels of Reg3α were unchanged during acute infection as compared to pre-infection levels, and actually decreased into chronic infection (P = 0.01)." (PMID 32426577, 2020). "At the peak of the infection, genes related to antimicrobial defense and barrier function, including Reg3a, Reg3g, Defb37, Defb40, Claudin-8, and Claudin-15, also showed altered expression, suggesting weakened antimicrobial protection and impaired tight junction integrity." (PMID 40630939, 2025). "Our findings support the presence of induced systemic inflammation and mucosal injury during non-invasive ETEC infection, notably marked by an increase in CRP and SAAt with a decreased truncation pattern in SAA1.1 and Reg3a during the early infection phase in the SP group." (PMID 38430452, 2024). "In the past decade, it has been determined that REG3A expression is regulated by injury, infection, inflammatory stimuli, and pro-cytokines via different signaling pathways, and it acts as a tissue-repair, bactericidal, and anti-inflammatory molecule in human diseases." (PMID 34811636, 2022). "Collectively, our data demonstrate that IL-17E-IL-17RB plays an essential role in inducing antibacterial protein Reg3a production in the early-phase of H. pylori of infection, which may contribute to host defense against H. pylori." (PMID 30692510, 2019).
metabolic disorder (3 papers, 2023 to 2025). "Despite a robust body of preclinical evidence supporting the involvement of REG3A in diverse pathological settings, including inflammation, tissue regeneration and metabolic disorders, its translation to clinical application remains nascent." (PMID 40723277, 2025). "In summary, REG3A-based interventions are emerging as promising tools in regenerative medicine, metabolic disorders, and potentially oncology, supported by early clinical safety and efficacy signals." (PMID 40723277, 2025). "From a translational perspective, REG3α could help identify individuals in an early “adaptive” phase of mucosal activation before overt metabolic disease develops." (PMID 41614735, 2025).
colorectal (1 paper, 2016). "However, no studies have yet demonstrated the exact role of REG3A on colorectal carcinogenesis and the details of the pathways through which signals REG3A exerted its function." (PMID 26646797, 2016).
REG3A also shares sentences with these, for which no sentence is quoted: fatty liver disease (2 papers); gastrointestinal disease (2); polymyositis (2); ulcerative colitis (2); alcoholic steatohepatitis (1); Alzheimer disease (1); anemia (1); astrocytoma (1); chronic liver failure (1); Cirrhosis (1); colon adenoma (1); congenital heart disease (1); digestive system cancer (1); endotoxemia (1); gastritis (1); gastrointestinal carcinomas (1); glioblastoma (1); H. pylori (1); heart failure (1); hematological malignancy (1); Hepatic steatosis (1); hepatoblastoma (1); inflammation (1); insulinoma (1); intestinal disorder (1); irritable bowel syndrome (1); metastasis (1); myocardial infarction (1); nesidioblastosis (1); neurodegenerative disease (1).
A further 10 diseases each share a sentence with REG3A in 1 paper.